CHI3L1 (chitinase 3 like 1)
Diseases named in the same sentence as CHI3L1 in open-access papers (continued):
Sharing a sentence is not in itself a finding about the gene and the disease.
endometriosis (7 papers, 2015 to 2024). The growth of functional endometrial tissue in anatomic sites outside the uterine body. "Endometriosis is a common reproductive disease among women and can be diagnosed and evaluated for severity on the basis of increased levels of Chi3l1." (PMID 39769202, 2024). "Protein YKL-40 (CHI3L1–chitinase-3-like protein 1, HC-gp-39–human cartilage glycoprotein-39, gp-38k, chondrex) is the subject of scientific research looking for new biomarkers of endometriosis." (PMID 34638893, 2021). "A positive correlation between serum Chi3l1 levels and the stage of endometriosis has been revealed, and the inflammatory process during endometriosis may result in elevated Chi3l1 levels." (PMID 39769202, 2024). "Further studies suggest that a triple combination panel of Chi3l1/IL-37/CA125 and a quadruple combination panel of Chi3l1/CA125/endocan/copeptin can provide more sensitive and specific diagnoses of the endometriosis stage, especially moderate-to-severe endometriosis." (PMID 39769202, 2024).
esophageal cancer (7 papers, 2014 to 2023). A primary or metastatic malignant neoplasm involving the esophagus. "CHI3L1 expression level was positively associated with tumor size, and elevated level of CHI3L1 in esophageal cancer tissues caused major changes ECM and cell junction gene programs." (PMID 34612767, 2021). "Consistently, our results show that the elevated expression of CHI3L1 in the transgenic mouse model for esophageal carcinoma is also associated with the upregulation of M2 macrophage markers." (PMID 34612767, 2021). "To validate the finding that CHI3L1 is upregulated in esophageal carcinoma and is associated with macrophage function, we analyzed CHI3L1 expression in a transgenic mouse model of esophageal carcinoma." (PMID 34612767, 2021). "A transgenic mouse model of esophageal carcinoma was used to validate CHI3L1 expression and its association with macrophage signature gene expression." (PMID 34612767, 2021). "We showed the upregulation of CHI3L1 in esophageal cancer tissues in comparison to normal esophageal tissues, and its upregulation was positively associated with tumor size." (PMID 34612767, 2021). "RNA-seq data in ESCA (esophageal cancer) project (162 esophageal cancer tissues) were used for the correlation analysis between immune cell signatures and CHI3L1 expression level using ssGSEA immune cell algorithm (GSVA package built-in algorithm)." (PMID 34612767, 2021). "We analyzed the expression level of CHI3L1 in 162 esophageal squamous cell carcinomas and 11 normal esophageal tissues, and found that CHI3L1 was highly expressed in esophageal cancer tissues (P < 0.001)." (PMID 34612767, 2021). "In this study, we aim to investigate the expression level of CHI3L1 in esophageal cancer and its correlation with immune cell types." (PMID 34612767, 2021). "We also found that CHI3L1 was significantly upregulated in esophageal cancer tissue samples (P < 0.001)." (PMID 34612767, 2021). "Together, these data suggest that macrophage represents as a dominant type of innate immune cells infiltrated in the esophageal carcinoma with high CHI3L1 expression." (PMID 34612767, 2021). "Specifically, analysis of immunological signatures and CHI3L1 expression indicated that CHI3L1 level was highly correlated with increased expression of macrophage signature genes in esophageal carcinoma." (PMID 34612767, 2021). "Esophageal carcinoma tissue (n = 6) and para-cancerous normal tissues (n = 6) were collected and qPCR analysis showed a significant upregulation of CHI3L1 in the tumor tissues." (PMID 34612767, 2021). "A study using ELISA assay to detect the concentration of chitinase 3-like 1 in the serum indicated that higher chitinase 3-like 1secreted by peri-tumoral macrophages in esophageal carcinoma had a significantly poor overall survival." (PMID 31238895, 2019). "The ROC analysis also indicates that CHI3L1 level could predict esophageal cancer with certain accuracy." (PMID 34612767, 2021). "However, the expression of CHI3L1 and its potential role in esophageal cancer remains to be elucidated." (PMID 34612767, 2021). "Collectively, our data indicates that the elevated level of CHI3L1 expression in esophageal cancer may favor the recruitment of macrophage in TME to support the progression of esophageal cancer." (PMID 34612767, 2021). "We observed high CHI3L1 expression in several cancers, including BLCA, esophageal carcinoma, lung adenocarcinoma, and thyroid carcinoma." (PMID 37958973, 2023). "However, the expression of CHI3L1 and its potential role in esophageal cancer remains unclear." (PMID 34612767, 2021). "We further applied receiver operating characteristic (ROC) curves to analyze the effectiveness of CHI3L1 expression levels in distinguishing esophageal cancer tissues from non-tumor tissues." (PMID 34612767, 2021).
Huntington disease (7 papers, 2022 to 2025). Huntington disease (HD) is a rare neurodegenerative disorder of the central nervous system characterized by unwanted choreatic movements, behavioral and psychiatric disturbances and dementia. "Reportedly, Chi3l1 levels are elevated both in the plasma and CSF of Huntington’s disease mouse models." (PMID 39769202, 2024). "In Huntington’s disease, CHI3L1 has been suggested as a potential biomarker of disease progression." (PMID 38177294, 2024).
meningitis (7 papers, 2007 to 2023). A disorder characterized by acute inflammation of the meninges of the brain and/or spinal cord. "Elevated levels of CHI3L1 have also been observed in patients with infectious diseases such as pneumonia, purulent meningitis, and E. coli infections." (PMID 37834128, 2023). "A study investigating patients with meningoencephalitis and meningitis revealed that levels of CHI3L1 in the CSF were significantly higher in the TBE meningoencephalitis group compared to the meningitis group." (PMID 37834128, 2023).
triple-negative breast carcinoma (7 papers, 2019 to 2025). An invasive breast carcinoma which is negative for expression of estrogen receptor (ER), progesterone receptor (PR), and human epidermal growth factor receptor 2 (HER2). "CHI3L1, which is generated from triple-negative breast cancer stem cells (TN-BCSCs), causes immunosuppression by improving CTLA4 expression in T cells via MAF and decreasing CD8+ T cell cytotoxicity." (PMID 40097979, 2025). "MDSCs secrete pro-metastatic factors such as MMP9 and chitinase 3-like 1 (CHI3L1) to promote triple-negative breast cancer (TNBC) stem cell function." (PMID 35003065, 2021). "In addition, the tumor-derived cytokine Chi3l1 induces the formation of NETs, which facilitates T-cell exclusion in triple-negative breast cancer." (PMID 39308692, 2024). "In triple-negative breast cancer mouse model, local and systemic levels of MMP-9, VEGF, chitinase-3-like protein 1 (CHI3L1) and Lipocalin-2 (LCN2) induced by TAMs mediate cancer metastasis." (PMID 31629410, 2019). "In triple-negative breast cancer, LCs recruit polymorphonuclear myeloid-derived suppressor cells (PMN-MDSCs) through the secretion of CCL22 and CXCL2, which, in turn, mediate the secretion of MMP9 and chitinase-3-like protein-1 (CHI3L1)." (PMID 39408880, 2024).
chronic kidney disease (6 papers, 2019 to 2024). Impairment of the renal function secondary to chronic kidney damage persisting for three or more months. "Chronic kidney disease (CKD) is associated with increased development of cardiovascular complications, and plasma Chi3l1 levels increase with CKD stage." (PMID 39769202, 2024).
coronary atherosclerosis (6 papers, 2014 to 2021). Atherosclerosis of the coronary vasculature. "We found that the expression of CHI3L1 was enhanced in aorta of patients with coronary atherosclerosis and its expression was significantly correlated with the atherosclerotic risk factors and the severity of CAD." (PMID 24729664, 2014). "Similar to their research, we studied the CHI3L1 protein expression in the aorta of patients with coronary atherosclerosis." (PMID 24729664, 2014). "In conclusion, the expression of CHI3L1 was enhanced in the aorta of patients with coronary atherosclerosis and its expression was significantly correlated with the atherosclerotic risk factors and the severity of CAD." (PMID 24729664, 2014). "In the present study we found that the expression of CHI3L1 was augmented in aorta of patients with coronary atherosclerosis and its expression was significantly correlated with the atherosclerotic risk factors and the severity of CAD as quantified by coronary angiograph." (PMID 24729664, 2014). "Also, CHI3L1 and TIM-1 have been found associated with the development of coronary atherosclerosis." (PMID 33439866, 2021).
food allergy (6 papers, 2021 to 2025). Gastrointestinal disturbances, skin eruptions, or shock due to allergic reactions to allergens in food. "Chitinase 3-like 1 (CHI3L1) protein levels are significantly higher in children with food allergy and ovalbumin (OVA)-sensitized mice than in healthy controls, and this has been linked to M2 macrophage polarization." (PMID 34394086, 2021). "In addition, in a food allergy mouse model, CHI3L1 expression is increased in the intestinal macrophages, which leads to M2-like macrophage polarization." (PMID 34612767, 2021).
malaria (6 papers, 2014 to 2022). Malaria is a serious and sometimes fatal disease caused by a parasite that commonly infects a certain type of mosquito which feeds on humans. "In this study, CHI3L1 was validated as an independent biomarker of morbidity and mortality in children with severe malaria that is associated with the presence and severity of AKI." (PMID 29448936, 2018). "Additional studies are required to validate the relationship between CHI3L1 and AKI in severe malaria and investigate the association between CHI3L1 and established biomarkers of AKI." (PMID 29448936, 2018). "Further, the majority of children were followed up to 6 months allowing us to evaluate the association between CHI3L1 and post-discharge mortality in children with severe malaria." (PMID 29448936, 2018). "The data in our study suggest that this malaria-mediated inflammation (i.e., increased sTNFRII and CHI3L1) may be associated with delayed neurocognitive development in exposed children." (PMID 34582452, 2021). "We identified several biomarkers of immune (IL-8, sTNFR1, sTREM-1, CHI3L1) and endothelial (Angpt-2, sFlt-1) activation associated with AKI in children with both malaria and NMFI." (PMID 35456111, 2022). "In the parent trial, malaria during pregnancy was associated with elevation of inflammatory mediators including sTNFRII, CRP, and CHI3L1 across pregnancy." (PMID 34582452, 2021). "At Visit 1, compared with uninfected women, malaria-infected women had significantly higher levels of CHI3L1, CRP, sICAM-1, IL-18BP, sTNFRII, and sEng and lower levels of Leptin (p ≤ 0.005)." (PMID 31574087, 2019). "Additional studies are needed to delineate the role between CHI3L1, alternative macrophage activation in severe malaria and its relationship with AKI and NO bioavailability." (PMID 29448936, 2018). "Elevated levels of CHI3L1 have been reported in Ugandan children with severe malaria, and further elevated in fatal malaria." (PMID 29448936, 2018). "At admission, children with CHI3L1 levels in the highest quartile had a median of 5 severe malaria criteria compared to 4 in children with the lowest three quartiles (p < 0.0001)." (PMID 29448936, 2018). "Plasma CHI3L1 levels were measured daily for 4 days in children admitted to hospital with severe malaria and at day 14 follow up." (PMID 29448936, 2018). "In order to explore potential pathophysiologic mechanisms linking elevated CHI3L1 and mortality in severe paediatric malaria, admission levels of CHI3L1 were compared with other host markers of immune and endothelial activation." (PMID 29448936, 2018). "CHI3L1 alone had excellent sensitivity (>90%) but poor specificity (<70%) for predicting mortality in children with severe malaria." (PMID 25047113, 2014). "Co-culture of P. falciparum with human peripheral blood mononuclear cells and the Plasmodium berghei ANKA experimental model of cerebral malaria were used to examine the role of CHI3L1 in severe malaria." (PMID 25047113, 2014). "In Ugandan children with malaria, plasma levels of CHI3L1 were elevated in severe disease and further increased in those who subsequently died of infection." (PMID 25047113, 2014). "Increased plasma CHI3L1 in severe and fatal human malaria prompted examination of CHI3L1 in malaria models." (PMID 25047113, 2014). "Using model systems, it was found that malaria parasites stimulated CHI3L1 production by human immune cells in vitro, and plasma and brain CHI3L1 increased during ECM." (PMID 25047113, 2014). "Although CHI3L1 was strongly associated with AKI, which is an established risk factor for mortality in severe malaria, the relationship between CHI3L1 and increased risk of death was independent of AKI status suggesting CHI3L1 is not simply a biomarker of kidney function." (PMID 29448936, 2018).
malaria (continued). "CHI3L1 is a novel biomarker of malaria-associated AKI and an independent risk factor for mortality that is associated with well-established pathways of severe malaria pathogenesis including inflammation, endothelial activation, and haemolysis." (PMID 29448936, 2018). "AKI is associated with higher mortality in paediatric severe malaria; therefore, the relationship between longitudinal time course of CHI3L1 in patients with and without AKI was investigated." (PMID 29448936, 2018). "Given the association of severe malaria with excessive TH1 inflammatory responses, it is reasonable to hypothesize that CHI3L1 levels would be increased in severe malaria infection, and would protect against immunopathology in experimental CM (ECM)." (PMID 25047113, 2014). "Inflammation is a known inducer of CHI3L1, and a well-established feature of severe malaria." (PMID 25047113, 2014). "The precise pathways mediating CHI3L1 induction by malaria remain undefined." (PMID 25047113, 2014). "Of relevance to malaria, CHI3L1 has been shown to modulate immune responses." (PMID 25047113, 2014). "Next, it was assessed whether CHI3L1 could prognosticate outcome among children with severe malaria, which could facilitate clinical triage and resource allocation." (PMID 25047113, 2014). "In children with both malaria and NMFI, there was evidence of endothelial activation (increased Angpt-2 and sFlt-1), as well as immune activation (increased sTNFR1, CHI3L1 and sTREM-1) in children with severe AKI (adjusted p < 0.05 for all)." (PMID 35456111, 2022). "In children with malaria and NMFI, there was an increase in CHI3L1, sTFNR1, sTREM-1, and Angpt-2 in the presence of severe AKI." (PMID 35456111, 2022). "The current study lends additional support to CHI3L1 and sTREM-1 as biomarkers of AKI, disease severity, and mortality in severe malaria." (PMID 35456111, 2022). "At time of presentation to hospital, plasma CHI3L1 was significantly higher in children with CM and SMA compared to uncomplicated malaria (p < 0.001), indicating that CHI3L1 levels reflect disease severity in malaria infection." (PMID 25047113, 2014). "CHI3L1 levels also correlated with markers of immune activation (CRP, sTREM-1, CXCL10/IP-10), endothelial activation (Ang-2, sICAM-1), and haemolysis (LDH, haem, haemopexin), pathways of injury that are well described in paediatric severe malaria." (PMID 29448936, 2018). "As CHI3L1 is produced by tubular cells in response to injury and remodelling, it may represent a novel biomarker of AKI in pediatric severe malaria." (PMID 29448936, 2018). "Plasma CHI3L1 was elevated in Ugandan children with CM and SMA compared to uncomplicated malaria." (PMID 25047113, 2014). "Although deletion of Chi3l1 did not alter key disease parameters or death in the P. berghei model of ECM, these findings do not exclude a role for CHI3L1 in human severe malaria because of model limitations and, potentially, the multiplicity of CHI3L1 functions." (PMID 25047113, 2014).
periodontitis (6 papers, 2019 to 2025). An acute or chronic inflammatory process that affects the tissues that surround and support the teeth. "and the cytokines chitinase 3-like 1, sIL-6Rα, sTNF-R1, and gp130/sIL-6Rβ might have the future potential to serve as a combined bacteria-host salivary biomarker panel for diagnosis of the chronic infectious disease periodontitis." (PMID 31281801, 2019). "Only one protein, Chitinase 3-Like-1 (also known as YKL-40), was significantly reduced in saliva of patients with moderate/severe periodontitis." (PMID 31072030, 2019). "In contrast, the salivary levels of Chitinase 3-like 1 were significantly (p = 0.041) lower in patients with moderate/severe periodontitis compared to no/mild periodontitis group." (PMID 31072030, 2019).
pulmonary hypertension (6 papers, 2019 to 2025). Increased pressure within the pulmonary circulation due to lung or heart disorder. "CHI3L1 may serve as a diagnostic biomarker for systemic sclerosis with pulmonary arterial hypertension and pulmonary hypertension associated with bronchopulmonary dysplasia." (PMID 38177294, 2024). "We hypothesize that CHI3L1 and its signaling pathways contribute to the vascular remodeling responses that occur in pulmonary hypertension (PH)." (PMID 35951428, 2022).
allergic asthma (5 papers, 2019 to 2025). A asthma with a basis in a pathological type I hypersensitivity reaction. "CHI3L1 is known to promote type 2 immune responses such as those that are seen in allergic asthma, and IL-13 plays a key role in these responses." (PMID 34747367, 2021). "MUC5B, ORMDL3, MUC5AC, CHI3L1, CLCA1, and IL-33 display a distinctly high non-specific relationship with allergic and non-allergic asthma." (PMID 33936056, 2021).
atopic dermatitis (5 papers, 2017 to 2025). "Previously, we found that suppressing CHI3L1 alleviated atopic dermatitis-like skin inflammation by inhibiting NF-κB-mediated ITGA5 expression in CHI3L1 knockout mice." (PMID 38177294, 2024). "CHI3L1/ITGA5 axis was related to treating atopic dermatitis." (PMID 36742137, 2023).
bacterial pneumonia (5 papers, 2014 to 2024). Acute infection of the lung parenchyma caused by bacteria (e.g., Streptococcus pneumoniae, Haemophilus influenzae, Chlamydia pneumoniae, Mycoplasma pneumoniae, and Legionella pneumophila). "Further, these studies provide CD44 and CHI3L1 as targetable mechanisms for treating bacterial pneumonia in those with AUD." (PMID 35634317, 2022). "In bacterial pneumonia, CHI3L1 activity promotes innate immune defenses by sensing oxidant stress, cytokines, growth factors and miRNAs in the extracellular environment." (PMID 35634317, 2022). "Alcohol and high CHI3L1 levels have been linked to the progression of liver injury and fibrosis, but not yet in alcohol and bacterial pneumonia." (PMID 35634317, 2022).